FADS2 (fatty acid desaturase 2)
Diseases named in the same sentence as FADS2 in open-access papers (continued):
Sharing a sentence is not in itself a finding about the gene and the disease.
colorectal cancer (6 papers, 2020 to 2025). A primary or metastatic malignant neoplasm that affects the colon or rectum. "Hsa_circ_0022383, also known as circRNA FADS2, is highly expressed in colorectal cancer and rheumatoid arthritis but downregulated in endometritis." (PMID 40626007, 2025). "FADS2 is overexpressed in colorectal cancer and promotes cancer cell proliferation by increasing the metabolism of oncogenic molecules related to colorectal tumorigenesis." (PMID 37849388, 2023). "FADS2 is a key enzyme in the production of polyunsaturated fatty acids and is more highly expressed in several cancers, including colorectal cancers." (PMID 36028991, 2022). "Finally, we detected a similar switch from poor to better survival correlated with FADS2 expression in high-grade pancreatic and mesenchymal-type colorectal cancers." (PMID 39009641, 2024). "FADS2 has been shown to overexpress in colorectal cancer and facilitate cancer cell proliferation by increasing the metabolism of PGE2, an oncogenic molecule associated with colorectal cancer tumorigenesis." (PMID 34249910, 2021).
glioma (6 papers, 2020 to 2024). A benign or malignant brain and spinal cord tumor that arises from glial cells (astrocytes, oligodendrocytes, ependymal cells). "In glioma, the expression of FADS2 was positively associated with stemness, cell cycle, DNA damage, and proliferation." (PMID 36788618, 2023). "The interrogation of human glioma gene expression showed the significant upregulation of FADS2, suggesting the underlying mechanism responsible for this observation." (PMID 36273646, 2022). "The enzymes required for essential fatty acid metabolism, fatty acid elongase 5 (ELOVL5), fatty acid desaturase 1 (FADS1) and fatty acid desaturase 2 (FADS2) are upregulated in low-grade glioma." (PMID 39251875, 2024). "In addition, inhibition of FADS2 as well as fatty acid elongase 2 (Elovl2), has been demonstrated to curb the growth of glioma stem cells." (PMID 36338708, 2022). "Nevertheless, it seems that FADS1 and FADS2 in glioma tumors have anti-neoplastic properties." (PMID 32392704, 2020). "It was also shown that CD133+ glioma stem cells from in vitro cultured neurospheres display elevated FADS1 and FADS2 activities and that SCD and FADS2 exhibit spatial heterogeneity with higher expression in the peritumoral area." (PMID 36338708, 2022).
coronary artery disease (5 papers, 2016 to 2023). "T alleles and TT genotypes of the FADS1/FADS2 variants are associated with coronary artery disease and ischemic stroke." (PMID 35736500, 2022). "The lead variant associated with estimated D6D activity, rs138194593, is located in an intronic region of the FADS2 gene and has been associated with FADS2 expression in blood from Estonian coronary artery disease patients." (PMID 30453627, 2018). "It has been reported that the fatty acid desaturase 1 (FADS1) and FADS2 genes play an important role in the adaptation of the Inuit diet and are associated with coronary artery disease, and the variants in these genes may affect the biosynthesis of ω-3 FAs." (PMID 37121469, 2023).
hepatocellular carcinoma (5 papers, 2019 to 2025). A malignant tumor that arises from hepatocytes. "Increased FADS2 expression is linked to hepatocellular carcinoma (HCC) and non-small cell lung cancer." (PMID 39478862, 2024). "FADS2 was found to be highly expressed in a subset of triple-negative breast cancer patients characterized by poorer prognoses 40; furthermore, donafenib was shown to downregulate FADS2, resulting in synergistic inhibition of hepatocellular carcinoma in both in vitro and in vivo models." (PMID 40535804, 2025). "An in vitro study demonstrated that the relative mRNA expressions of FADS2 (D6D) and FADS1 (D5D) genes were lower in vitamin B6-restricted human hepatoma cells than in control." (PMID 33572554, 2021). "Indeed, in this paper they showed that many cancer cells activate lipid-synthesis pathways to support their rapid proliferation, especially hepatocellular carcinoma implicating two enzymes SCD and FADS2." (PMID 31717414, 2019). "In addition, we have previously reported that a combination of SCD and FADS2 inhibition successfully curbs tumor growth in an orthotopic hepatocellular carcinoma model, albeit not necessarily involving the same mechanism." (PMID 36338708, 2022).
Infertility (5 papers, 2020 to 2025). "Based on the previous studies performed on mammals, infertility has been marked as a hallmark of FADS2 deficiency." (PMID 35456508, 2022). "In male FADS2 knockout mice, acrosome formation fails during the spermiogenesis of round sperm into elongated sperm, and therefore causes infertility." (PMID 34445473, 2021). "Accordingly, the body of literature reports that both FADS2 and ELOVL2 knockout male mice are infertile since they cannot sustain sufficient levels of DHA, n-6 DPA and other PUFAs in the testis." (PMID 35173269, 2022). "Studies on δ6-desaturase (FADS2) knockout mice have indicated that the absence of initial steps in PUFA synthesis can lead to spermatogenesis stasis and infertility." (PMID 40078211, 2025).
acne (4 papers, 2021 to 2024). An inflammatory process of the sebaceous glands which is characterized by comedones, nodules, papules and/or pustules on the skin. "Recent genome-wide association studies and meta-analysis have shown that FADS2 is a risk gene for acne vulgaris." (PMID 38371936, 2024). "In particular, the fatty acid metabolism pathway shows enrichment of PLA2G4A/FADS2, which further supports the correlation between four gut microbes and acne vulgaris." (PMID 38371936, 2024). "The biological annotation analysis indicates that we have identified 3 pairs of associated genes between gut microbiota and acne vulgaris, including PLA2G4A/FADS2, TIMP3/ADAMTS9 and ZC3H3/CPSF4L." (PMID 38371936, 2024). "Two novel acne associated loci, identified in this study, contain genes encoding enzymes involved in lipid metabolism: FADS1/FADS2 and FASN." (PMID 36922633, 2024). "Lower FADS2 expression in skin is described in inflammatory skin conditions (acne, dermatitis, psoriasis)." (PMID 35219001, 2022). "This evidence reinforces the involvement of the FADS2 pathway in the promotion of the sebum synthesis and occurrence of acne." (PMID 34400712, 2021). "After conducting biological annotation, we identified six genes (PLA2G4A, FADS2, TIMP17, ADAMTS9, ZC3H3, and CPSF4L) that may be associated with the pathogenic gut microbiota of acne vulgaris patients." (PMID 38371936, 2024). "The enhanced DNL in acne may cause a prominent decrease in synthesis of anti-inflammatory PUFA molecules like EPA, DHA and DGLA, because palmitic acid competes with linoleic and α-linolenic acids for FADS2-mediated Δ6-desaturation." (PMID 36922633, 2024).
acute myocardial infarction (4 papers, 2010 to 2024). Necrosis of the myocardium, as a result of interruption of the blood supply to the area. "More recently, genetic profiling of fatty acid desaturase 2 (FADS2) polymorphisms has been shown to identify patients who may benefit from high-dose omega-3 PUFAs for cardiac remodeling after acute myocardial infarction." (PMID 36276836, 2022).
colon carcinoma (4 papers, 2013 to 2021). "Interestingly, FADS2 is an enzyme involved in arachidonic acid production, and it may promote prostaglandin E2 production in colon tumor cells, which could be linked with increased colon cancer cell proliferation." (PMID 34206240, 2021). "Along with SCD, we also found FADS2 expression and activity to be significantly increased in colon tumor cells." (PMID 34206240, 2021). "Together with FADS2 and FADS1, levels of ELOVL2 and 5 have been found to be increased in colon tumors." (PMID 34206240, 2021). "Our data are in line with recently observed upregulation of FASN and FADS2 in colon tumors, where particularly the overexpression of FASN was negatively associated with CRC patient survival." (PMID 34206240, 2021).
Hypertension (4 papers, 2021 to 2025). The presence of chronic increased pressure in the systemic arterial system. "We aimed to determine whether the FADS2 rs174583 variant interacts with the Dietary Approach to Stop Hypertension (DASH) score and Mediterranean dietary score (MDS) to influence cardio-metabolic risk factors among obese adults." (PMID 34164423, 2021).
lipid metabolism disorders (4 papers, 2017 to 2025). "This study identifies FADS1, FADS2, GLB1, and PNPLA3 as key genes integrating both lipid metabolism disorders and inflammation in MAFLD, with potential diagnostic implications." (PMID 41007773, 2025). "Moreover, KLF10-silenced groups exhibited overexpression of Cyb5r3, Fads1, and Fads2, which are involved in diseases such as lipid metabolism disorder." (PMID 34869587, 2021).
liver cancer (4 papers, 2019 to 2022). An epithelial or non-epithelial malignant neoplasm that arises from the liver. "After evaluating the correlation of these fatty acid‐related genes with the ES cell‐like gene expression signatures in HCC, we found that four genes, including ACSL3, ACSL4, FADS1, and FADS2, were highly related to stem cell characteristics in liver cancer." (PMID 35603967, 2022). "Moreover, fatty acid desaturase 2 (FADS2), and its product sapienate, are also upregulated in lung and liver cancer tissues." (PMID 31936134, 2020). "The tumor environment such as fibrosis, hypoxia, dysregulated metabolism might also influence the liver cancer cell regulation of SCD and FADS2 enzyme activities especially in the case of HCC developed from NASH stage." (PMID 31717414, 2019).
liver fibrosis (4 papers, 2019 to 2025). "Altogether 96 genes implicated in YYHXD therapy for hepatic fibrosis were identified from RNA sequencing data, with Fasn and Fads2 being potential key genes affected by treatment." (PMID 38813108, 2024). "Increased expression of FADS2 significantly augments the development of hepatic fibrosis, causing accelerated synthesis of unsaturated aliphatic acids in hepatocytes and an imbalance of intracellular lipid metabolism." (PMID 38813108, 2024). "The q-PCR results indicated that expression of Fasn and Fads2 mRNA in hepatic tissue of CCl4-induced hepatic fibrosis rats was notably higher than that of normal rats, while YYHXD significantly inhibited this increase in a dose-dependent manner." (PMID 38813108, 2024). "Additionally, the highly expressed genes GRIA3, FABP4, FADS2, and PRKAA2 have been implicated in lipid metabolism and liver fibrosis." (PMID 38263097, 2024). "The results suggested that FASN and FADS2 may function as pivotal players in the treatment of hepatic fibrosis by YYHXD." (PMID 38813108, 2024). "Although altered DNA methylation in several other genes has been associated with NASH and liver fibrosis, DNA methylation in neither cg06781209 nor cg07999042 in FADS2 correlated with fibrosis or inflammation in the liver." (PMID 30654845, 2019). "KA effectively inhibits both FADS2 and CYP4A8, blocking these signaling pathways, thereby reducing HSC activation and fibrosis markers such as HA and PC-III, demonstrating its anti-liver fibrosis properties." (PMID 40950574, 2025).
non-small cell lung carcinoma (4 papers, 2020 to 2025). A group of at least three distinct histological types of lung cancer, including non-small cell squamous cell carcinoma, adenocarcinoma, and large cell carcinoma. "In other types of tumors, FADS1 and FADS2 exhibit oncogenic properties, for example in non-small-cell lung cancer, where the lower expression of FADS1 is associated with worse prognosis." (PMID 32392704, 2020).
psoriasis (4 papers, 2022 to 2025). An autoimmune condition characterized by red, well-delineated plaques with silvery scales that are usually on the extensor surfaces and scalp. "Functional analyses revealed that FADS2 deficiency in keratinocytes enhanced inflammatory responses by activating the NF‐κB pathway to recruit neutrophils to the psoriasis lesions, likely through disruption of the n‐3 fatty acids desaturation pathway involved in DHA biosynthesis." (PMID 40878384, 2025). "Moreover, mice with keratinocyte‐specific Fads2 knockdown exhibited increased mRNA levels of psoriasis‐associated inflammatory mediators, including Il17a, Il1b, and Cxcl1, in both the dorsal and ear skin, and greater neutrophil infiltration was confirmed by flow cytometry." (PMID 40878384, 2025). "Our findings revealed a functional PPARα‐FADS2 regulatory axis that governs keratinocyte‐intrinsic inflammatory responses in psoriasis." (PMID 40878384, 2025). "Consistent with this, elevated NF‐κB phosphorylation was evident in the IMQ‐induced psoriasis‐like skin lesions after Fads2 knockdown." (PMID 40878384, 2025). "To investigate the functional role of FADS2 in psoriasis, we used a mouse ear model of IMQ‐induced psoriasis‐like dermatitis." (PMID 40878384, 2025). "In the imiquimod (IMQ)‐induced psoriasis‐like mouse model, FADS2 expression in keratinocytes was significantly reduced in skin lesions and continued to decrease as the disease progressed." (PMID 40878384, 2025). "Collectively, these results demonstrated that silencing Fads2 amplified psoriasis‐like skin inflammation and promoted neutrophil infiltration, thereby underscoring FADS2 as a critical negative regulator of psoriatic inflammation." (PMID 40878384, 2025). "Collectively, these results establish FADS2 as an essential downstream effector for PPARα‐mediated immune modulation in psoriasis." (PMID 40878384, 2025). "Keratinocyte‐intrinsic Fads2 knockdown exacerbates imiquimod‐induced psoriasis‐like dermatitis, which is marked by enhanced neutrophil recruitment and NF‐κB activation, whereas Fads2 overexpression exerts protective effects and alleviates skin inflammation." (PMID 40878384, 2025). "Consistent findings were observed in IMQ‐induced murine psoriasis, where both PPARα and FADS2 expression were reduced in lesional epidermis compared to controls." (PMID 40878384, 2025). "Together, these findings uncover a PPARα‐FADS2‐DHA‐NF‐κB axis that links lipid metabolism to immune regulation in psoriasis, highlighting a potential therapeutic strategy for restoring cutaneous immune homeostasis." (PMID 40878384, 2025). "FADS2 expression is consistently reduced in keratinocytes from patients with psoriasis and in mouse models." (PMID 40878384, 2025). "Although this study provides new insights into the immunometabolic role of keratinocyte‐intrinsic FADS2 in psoriasis, it has several limitations." (PMID 40878384, 2025). "PPARα transcriptionally activates FADS2, and its activation alleviates inflammation in a FADS2‐dependent manner, highlighting a therapeutic axis to restore immune homeostasis in psoriasis." (PMID 40878384, 2025). "Collectively, these findings revealed a novel anti‐inflammatory role of FADS2 in psoriasis by limiting NF‐κB activation and disrupting the keratinocyte‐neutrophil inflammatory loop." (PMID 40878384, 2025). "In conclusion, our study reveals that FADS2 is a critical link between lipid metabolism and keratinocyte‐mediated inflammation in psoriasis." (PMID 40878384, 2025). "These were attributed to disease-risk loci including loci in or near NOS2 (psoriasis), TLR1 (eczema and allergic disease phenotypes), and FADS2 (vitiligo)." (PMID 39137780, 2024). "Among these, only FADS2 exhibited consistent downregulation at both mRNA and protein levels in lesional skin, particularly in keratinocytes, corroborating previous findings on the dysregulation of lipid metabolism in psoriasis." (PMID 40878384, 2025).
psoriasis (continued). "Functionally, our in vivo experiments showed that keratinocyte‐specific Fads2 knockdown in the IMQ‐induced psoriasis mouse model aggravated skin inflammation, increased keratinocyte proliferation, elevated the levels of inflammatory factors and chemokines, and promoted neutrophil infiltration." (PMID 40878384, 2025). "Taken together, these findings demonstrate that FADS2 is consistently and specifically downregulated in the keratinocytes of both human psoriatic lesions and murine psoriasis‐like skin, suggesting a potential involvement of FADS2 dysregulation in the pathogenesis of psoriasis." (PMID 40878384, 2025). "Considering the pivotal role of keratinocytes in psoriasis pathogenesis, we systematically investigated the expression pattern, functional significance, and regulatory mechanism of FADS2 in psoriatic keratinocytes using clinical samples as well as in vitro and in vivo models." (PMID 40878384, 2025). "Conversely, FADS2 overexpression attenuated M5‐induced inflammation, suggesting that FADS2 might mitigate the severity of psoriasis by modulating inflammatory responses in keratinocytes through NF‐κB signaling pathways, limiting excessive cytokine production and immune cell infiltration." (PMID 40878384, 2025). "Furthermore, inflammatory cytokines relevant to psoriasis pathogenesis, including Il17a, Tnfa, and Il1b, as well as neutrophil‐attracting chemokines, such as Cxcl1 and Csf3, were significantly upregulated at the mRNA level in Fads2‐silenced skin lesions compared to controls." (PMID 40878384, 2025). "Taken together, these data suggested that FADS2 maintains PUFA metabolic homeostasis, particularly DHA synthesis, to prevent keratinocyte‐driven inflammation in psoriasis." (PMID 40878384, 2025). "The upregulation of genes such as ELOVL3 and PECR in non‐lesional skin and ELOVL3 and FADS2 in plaque skin may improve lipid barrier function, suggesting that bevacizumab could potentially alleviate epidermal barrier dysfunction and limit disease progression in psoriasis." (PMID 39624732, 2024). "Conversely, epidermal overexpression of Fads2 via AAV‐K14‐flag‐Fads2 delivery led to a marked upregulation of both FADS2 mRNA and protein levels, and markedly alleviated IMQ‐induced psoriasis‐like inflammation." (PMID 40878384, 2025). "Together, these findings highlight the critical role of FADS2 in inflammatory signaling of keratinocytes by regulating PUFA metabolism and suggest that targeting lipid metabolic reprogramming, specifically via the FADS2‐DHA axis, may represent a promising therapeutic strategy for psoriasis." (PMID 40878384, 2025). "To assess whether FADS2 is required for PPARα‐mediated suppression of psoriatic inflammation in vivo, we knocked down Fads2 using siRNA and administered WY14643 in IMQ‐induced psoriasis‐like skin lesions." (PMID 40878384, 2025).
schizophrenia (4 papers, 2013 to 2025). A major psychotic disorder characterized by abnormalities in the perception or expression of reality. "The FADS1 and FADS2 variants used in this study satisfied HWE within the schizophrenia and bipolar populations as well as in the combined sample (all P > 0.1)." (PMID 24455201, 2013). "Therefore, it was reassuring to identify the chr17q21.31, chr3p21.1, and FADS1/FADS2 loci, which are associated with schizophrenia, cognition, and household income; cognition; and metabolic traits, respectively, as linking these co-occurring traits to ADHD." (PMID 40000109, 2025). "Similarly, a network analysis of ADHD-associated genetic variants identified genomic regions (e.g., chr17q21.31, FADS1/FADS2, chr3p21.1) at the intersection of ADHD with co-occurring traits (e.g., schizophrenia, metabolic traits, and intelligence)." (PMID 40000109, 2025). "Interestingly, we identified genes associated with fatty acid metabolism amongst VMPs with concordant changes in blood and brain, including HSD17B4, CYP4V2, FADS2, and SCD, indicating altered DNA methylation variance may impact fatty acid metabolism in these tissues in schizophrenia." (PMID 39271751, 2025).